IFNG (interferon gamma)
Diseases named in the same sentence as IFNG in open-access papers (continued):
Sharing a sentence is not in itself a finding about the gene and the disease.
hemophagocytic lymphohistiocytosis (55 papers, 2014 to 2026). "The main cytokines involved are interleukin (IL)-10, IL-6 and interferon gamma, also described to be linked to hemophagocytic lymphohistiocytosis (HLH)." (PMID 31921126, 2019). "As IFNγ is an activator of macrophages, it has a central role in the pathogenesis of hemophagocytic lymphohistiocytosis (HLH), a life-threatening condition caused by overactivation of the immune system resulting in hypercytokinemia, hyperinflammation, and multi-organ failure." (PMID 36401314, 2022). "Anti IFNγ mAbs developed by others translated to Emapalumab®, a drug approved in 2018 for primary hemophagocytic lymphohistiocytosis (HLH)." (PMID 36875111, 2023). "Emapalumab is an interferon gamma blocking antibody used to treat primary hemophagocytic lymphohistiocytosis." (PMID 36093185, 2022). "Hemophagocytic lymphohistiocytosis (HLH) is a life-threatening condition of immune dysregulation primarily driven by the cytokine interferon gamma." (PMID 36401314, 2022). "IFNγ has an essential effect on macrophage activation and clearly a pathogenic role in MAS considering that Emapalumab, which is an anti-IFNγ monoclonal antibody, has been recently approved for the treatment of hemophagocytic lymphohistiocytosis." (PMID 33284430, 2021). "SARS-CoV-2 increases interferon gamma, tumor necrosis factor-α, macrophage inflammatory protein-1 alpha, IL-2, IL-6, IL-7, IL-10, in patients, that show a form of secondary hemophagocytic lymphohistiocytosis or macrophage activation syndrome (sHLH/MAS)." (PMID 33494816, 2021). "Aim of this study was to investigate the activation of the IFNγ pathway in the affected liver and in the blood of patients with secondary hemophagocytic lymphohistiocytosis (sHLH)." (PMID 31846457, 2019). "They identified MILR1 and FLT3 as pre-infusion biomarkers predictive of severe CRS and noted that CRS may be an IFNγ-driven process with a protein signature overlapping with hemophagocytic lymphohistiocytosis." (PMID 40004863, 2025). "Hemophagocytic lymphohistiocytosis (HLH), a subtype of severe cytokine release syndrome, is associated with higher disease burden, pre-infusion NK-cell lymphopenia and persistent elevation of HLH-related cytokines including IFNγ, IL-1β and IL-18." (PMID 38711850, 2024). "IFNg appears central to the pathogenesis of rare, hyperinflammatory states like Hemophagocytic Lymphohistiocytosis (HLH) and Macrophage Activation Syndrome (MAS), and IL-18 is both a biomarker of MAS and may be central to its pathogenesis." (PMID 36096831, 2022). "Hemophagocytic lymphohistiocytosis (HLH) is a hyperactivation syndrome associated with the overactivation of macrophages, which produce enormous amounts of tumor necrosis factor-alpha and interferon-gamma." (PMID 36185842, 2022). "The search was conducted, for articles published from January 1, 1970 up to September 29, 2011, using combinations of the following key words and or their equivalents; Hemophagocytic syndrome, macrophage activation syndrome, interferon-gamma and thrombotic microangiopathy." (PMID 27047804, 2016). "Evidence Acquisition: Directory of Open Access Journals (DOAJ), EMBASE, Google Scholar, PubMed, EBSCO, and Web of Science with keywords relevant to; Hemophagocytic syndrome, macrophage activation syndrome, interferon-gamma and thrombotic microangiopathy, have been searched." (PMID 27047804, 2016). "Interferon gamma (IFN-γ) is the main cytokine driving organ dysfunction in Familial Hemophagocytic Lymphohistiocytosis (FHL)." (PMID 35671274, 2022). "Blood levels of IL-1β and IFNγ are typically upregulated, and an extremely high IL-18 can be measured, differentiating AIFEC from hemophagocytic lymphohistiocytosis (HLH)." (PMID 39618694, 2024). "The clinical importance of IFNγ as an inflammatory mediator is evident; an anti-IFNγ antibody (Emapalumab) has been FDA approved for treating hemophagocytic lymphohistiocytosis, which is driven by IFNγ signaling." (PMID 38130991, 2023).
hemophagocytic lymphohistiocytosis (continued). "Overproduction of interferon-gamma is a major driver of hyperinflammation in murine models of MAS and primary hemophagocytic lymphohistiocytosis." (PMID 36891226, 2023).
bacteremia (54 papers, 2008 to 2025). "Subsequently, we were able to demonstrate that the MSSA isolates persisted in experimental in vivo bacteremia model, in part, by inducing a pathogenic IFNγ response." (PMID 39878522, 2025). "Together this demonstrates that the pIB485-like encoded SAgs can promote excessive IFNγ production to promote bacterial persistence during experimental bacteremia." (PMID 39878522, 2025). "The present case series is the first reporting the use of IFNγ in adult and pediatric bacterial sepsis, including septic shock patients with associated cytokines level modifications and immunophenotyping." (PMID 31690258, 2019). "First, we found a number of positive associations with IFNγ, probably as a response to the bacteremia of the mucosa and/or the development of pathobionts following the damage of the duodenal wall by the parasites." (PMID 27438701, 2016). "Mice deficient in the expression of CD40 have been shown to have improved survival during bacterial sepsis as a result of decreased induction of IL-6, IL-10, IL-12 and IFNγ expression." (PMID 21949840, 2011). "Conversely, lower abundance of IFNG, Flt3L and TNFB (OR 0.84, 0.59, and 0.56, respectively) were observed in the case group, indicating that reduced levels of these proteins in plasma are associated with poor prognosis in patients with bacteremia." (PMID 41298591, 2025). "In light of the profound elevations in IL1β and IFNγ, the authors credit the use of anakinra for the positive outcomes observed, where all cases of HLH resolved (with one mortality due to bacterial sepsis) and suggest considering the use of emapalumab, a monoclonal antibody targeting IFNγ." (PMID 37232836, 2023). "Early IFNγ production in human blood controls intracellular S. Typhimurium infections and reduces the threat of the extracellular spread of the disease along with bacteremia." (PMID 31134022, 2019). "This phenotype was in contrast to experimental bacteremia studies where the SEB and SEC staphylococcal superantigens promoted liver abscess formation through a CD4-dependent and excessive IFNγ response." (PMID 39840991, 2025). "Combination therapy of nivolumab and interferon gamma (IFN-γ) has been reported to reverse immune suppression during fungal and bacterial sepsis by boosting lymphocyte count, monocyte activation, and CD8+ T cells." (PMID 38127685, 2023). "Furthermore, we associated IFNγ/IL10 to the bacterial load in critical ill patients, and compared publically available data of patients with and without bacteremia." (PMID 33767693, 2021).
chronic granulomatous disease (54 papers, 2009 to 2026). Chronic granulomatous disease (CGD) is a rare primary immunodeficiency, mainly affecting phagocytes, which is characterized by an increased susceptibility to severe and recurrent bacterial and fungal infections, along with the development of granulomas. "Interferon-gamma (IFN-γ), a key immunoregulatory cytokine, exhibits profound stimulation of T cell immunity, which is commonly involved in the reduction of the frequency and severity of serious infections associated with chronic granulomatous disease." (PMID 35105915, 2022). "For patients with chronic granulomatous disease (CGD) or defects of the IL-12/IFN-γ axis, interferon gamma (IFN-γ) is administered." (PMID 39274292, 2024). "Adjuvant therapy with recombinant interferon-gamma (rIFN-γ) has shown to be effective in BCG-osis associated with some types of MSMD and chronic granulomatous disease (CGD)." (PMID 35232430, 2022). "IFNγ is medically used for osteopetrosis and chronic granulomatous disease, the antibody against IFNγ emapalumab for the treatment of haemophagocytic lymphohistiocytosis." (PMID 33063247, 2020). "These include stimulants of the immune system such as interferon gamma, which has been used to enhance immune response and decrease infections in the treatment of the inherited immune deficiency chronic granulomatous disease (CGD)." (PMID 26114124, 2015). "IFNγ, is used principally for the treatment of chronic granulomatous disease (CDG), a rare congenital disorder characterized by a lack of superoxide and hydrogen peroxide production by macrophages and susceptibility to bacterial and fungal infections." (PMID 27713294, 2010). "However, the observation that IFNγ increased superoxide production from monocyte-derived macrophages in vitro led to interest in using it in therapy for chronic granulomatous disease (CGD)." (PMID 28848545, 2017). "Interferon-gamma (IFN-γ) decreases infections in chronic granulomatous disease (CGD) with variably incomplete restoration of the fundamental CGD defect, converting oxygen to microbicidal oxidants during phagocytosis." (PMID 40920799, 2025). "Some experience with this drug has been gained in patients with chronic granulomatous disease (CGD), an immunodeficiency in which treatment or prophylaxis with IFNγ is used to treat or prevent infections, respectively." (PMID 35986347, 2022). "IFNγ-1b parenteral treatment mimics endogenous IFN-γ action in enhancement of phagocytosis and restoration of phagocyte NADPH oxidase system in patient with chronic granulomatous disease." (PMID 36911685, 2023). "Interferon-gamma (IFN-γ) is the only type II interferon and is FDA-approved for the treatment of two rare pediatric diseases, osteopetrosis and chronic granulomatous disease." (PMID 37500647, 2023). "IFNγ is used for refractory S. aureus infections in chronic granulomatous disease (CGD)." (PMID 27093273, 2016). "The antiviral effects of IFNγ are less well-studied, but this protein is a FDA-approved therapy for chronic granulomatous disease and osteopetrosis." (PMID 26562011, 2015). "A 23-year-old male with a known history of chronic granulomatous disease (CGD) since childhood—initially presenting with granulomatous lesions of the buccal mucosa and axillary region—had been maintained on itraconazole, cotrimoxazole prophylaxis, and interferon-gamma injections." (PMID 41479599, 2026). "All patients were assessed in search of primary immunodeficiencies such as chronic granulomatous disease (CGD), interleukin 12-interferon gamma axis defect and infection by HIV, without finding any of these pathologies." (PMID 34399724, 2021).
osteosarcoma (54 papers, 2003 to 2026). A usually aggressive malignant bone-forming mesenchymal neoplasm, predominantly affecting adolescents and young adults. "In osteosarcoma, T-cells produce IFNγ that express PD-L1, and immune tolerance may be caused by a negative feedback loop through the PD-L1." (PMID 31914969, 2020). "Our findings showed that when engaging with autologous undifferentiated sarcoma and osteosarcoma cells, attIL12-TILs had markedly higher IFNγ production compared to control TILs via dual activation of the attIL12-CSV and TCR-HLA interactions." (PMID 39574893, 2024). "In vivo experiments using M1 activated and polarised macrophages with interferon-gamma showed that the combination with liposomal MTP-PE resulted in cell death of human osteosarcoma cell lines." (PMID 35672690, 2022). "In this study, we found that IFNγ enhances the expression of PD-L1 in osteosarcoma and the result is compatible with other reports." (PMID 31914969, 2020). "In addition, macrophages polarized in vitro with GM-CSF and further activated with MTP-PE and IFNγ are capable of inhibiting osteosarcoma growth by producing soluble factors, although independent of TNFα or IL-1β." (PMID 38919608, 2024). "We discovered that IFNγ increased PD-L1 expression on the surface of osteosarcoma cell lines." (PMID 31914969, 2020). "The expression of the ligand of PD-1 (i.e., PD-L1) on the surface of osteosarcoma was reported, and in our research, interferon gamma (IFN-γ), which is one of the inflammatory cytokines, increases the expression of PD-L1 on the surface of osteosarcoma in vitro." (PMID 32664248, 2020). "It is known that IFNγ is produced by inflammatory cells such as T cells and NK cells, and this in vitro result shows the possibility that adaptive PD-L1 expression is occurring in response to inflammation of osteosarcoma." (PMID 31914969, 2020). "A study analyzing osteosarcoma biopsies found that while CD8+ T cells were present in the TME, they lacked the ability to proliferate and secrete effector cytokines such as interferon-gamma (IFN-γ) and tumor necrosis factor-alpha (TNF-α)." (PMID 40170852, 2025). "The expression of Neuronal pentraxin (NPTX2) is negatively correlated with the expression of GZMB and IFNG, Knockdown of NPTX2 in osteosarcoma cells inhibited tumor growth and increased tumor cell apoptosis." (PMID 36204682, 2022). "Beside these, we do not see any significant correlation between expression levels of CD274 and PDCD1LG2 genes, that encodes PD-L1 and PD-L2 respectively, with the expression levels of PDCD1 and IFNG, and the percentage of CD8 T cells in osteosarcoma tumors." (PMID 33757216, 2021).
encephalitis (53 papers, 2010 to 2025). An acute inflammatory process affecting the brain parenchyma. "This founding is consistent with the reports that blocking the IFNγ‐induced JAK/STAT pathway can revise synaptic loss in viral encephalitis." (PMID 38494844, 2024). "Cytokines such as M-CSF and the B-cell markers CXCL13 and BAFF tend to be elevated in autoantibody-associated disorders, whereas interferon gamma (IFN-γ) is elevated mainly in viral encephalitis." (PMID 37919735, 2023). "IFNγ is an important immunoregulator, as shown by unchecked infiltration of neutrophils and fatal encephalitis in HSV-infected mice deficient in IFNγ." (PMID 31514273, 2019). "Studies of other encephalitis-associated viruses have shown that IFNγ and TNFα can play a critical role in controlling viral replication in the CNS." (PMID 24922480, 2014). "Nevertheless, some markers differed in concentration in CSF samples, such as IFNγ and Neurogranin; these were significantly higher in patients with encephalitis." (PMID 35458486, 2022). "IFNγ deficiency caused no changes to viral load or SLEV-induced encephalitis and did not change the expression of ISGs in the brain." (PMID 33410731, 2021). "This resulted in uncontrolled expansion and infiltration of pathogenic neutrophils into the CNS causing fatal encephalitis in IFNγ deficient (GKO) but not wildtype mice." (PMID 29352287, 2018). "Accumulating literature in both rodent models and human encephalitis implicate that manipulation of IL-10 and IFNγ may have broad implications to treat encephalitis more broadly." (PMID 30619363, 2018). "Thus, our study reveals a novel regulatory role for IFNγ in the control of G-CSF induced neutrophilia and further illuminates its role in protection from viral encephalitis." (PMID 29352287, 2018). "Our studies reveals a novel, complex interplay among IFNγ, G-CSF and IL-10, which highlights the opposing roles of G-CSF and IFNγ in regulation of innate inflammatory responses in a murine viral encephalitis model and reveals G-CSF as a potential therapeutic target." (PMID 29352287, 2018). "Interestingly, we also detected a significant increase in IFNγ and Neurogranin in the CFS of encephalitis patients." (PMID 35458486, 2022). "Only one other study has assessed profiles between encephalitis aetiologies and identified a higher concentration of IFNγ and TNFR1 in 13 patients with HSV than 15 with ‘non-herpetic limbic encephalitis’." (PMID 26808276, 2016). "IFNγ can inhibit the growth of JEV in the central nervous system, which might be related to the absence of encephalitis-like symptoms in C56BL/6J on 9 dpi." (PMID 40855992, 2025).
Cachexia (52 papers, 2005 to 2026). Severe weight loss, wasting of muscle, loss of appetite, and general debility related to a chronic disease. "Cancer cachexia is mainly caused by diminished oral intake and catabolic factors secreted by tumors, including interferon-gamma, interleukins, and tumor necrosis factor." (PMID 32083001, 2020). "Chronic Poly I:C treatment, via activation of Tlr3 and the RIG-I-like receptors, results in the production of IL-6 and IFNγ that can, when provided chronically as a model for cachexia, lead to a progressive weight loss." (PMID 25856311, 2015). "Cytokines that have been implicated in the development of cachexia include IL-6, IL-1, TNFα, and interferon-gamma (IFN-γ)." (PMID 21832306, 2011). "The role of IFNγ in cachexia is also not fully understood; however, it has been shown to synergize with TNF‐α to promote muscle wasting." (PMID 39764565, 2025). "We investigated the effects of HICA on mouse C2C12 myotubes under normal conditions and during cachexia induced by co-exposure to TNFα and IFNγ." (PMID 34371902, 2021). "The condition cachexia is mimicked by co-exposure to TNFα and IFNγ, and it induces decreasing of the diameters of C2C12 myotubes, as seen in skeletal muscle atrophy." (PMID 34371902, 2021). "TNFα, IL-6, IL-8, IL-1β, and IFNγ are considered to be the major inflammatory mediators of cancer-induced cachexia, which have been demonstrated to be elevated in various animal models of cancer." (PMID 32722688, 2020). "Tumor necrosis factor-alpha (TNF-α), interleukin 1 (IL-1), interleukin 6 (IL-6) and interferon-gamma (IFN-γ) are the main cytokines that are thought to be involved in the evolvement of cachexia, in general." (PMID 32655411, 2020). "Several studies have linked cachexia to increased plasma levels of proinflammatory cytokines such as interleukin (IL) 1β, IL6, tumor necrosis factor-alpha (TNF-α), and interferon-gamma (IFN-γ)." (PMID 32547603, 2020). "Numerous inflammatory cytokines are involved in the etiology of cachexia, including tumor necrosis factor alpha, interleukin (IL)-6, IL-1 and interferon gamma indicating that systemic inflammation plays a central role in cancer-associated cachexia." (PMID 31466311, 2019). "A popular in vitro model of cachexia involves the treatment of C2C12 myotubes with IFNγ and TNFα (IT) for 72 h, recapitulating many facets of the cachectic muscle." (PMID 29849089, 2018). "The primary catabolic mediators of cachexia include proinflammatory cytokines such as tumor necrosis factor alpha (TNFα), interferon gamma (IFNγ), and interleukin‐6 (IL‐6)." (PMID 28264935, 2017). "Elevated levels of serum inflammatory cytokines, such as IL-6, TNF-α and IFNγ, have been shown to impact myogenic and nuclear receptor signaling pathways in cancer-induced cachexia." (PMID 24782788, 2014). "In this study, we tested our hypothesis that HICA would attenuate the myotube atrophy that accompanies a decrease of protein synthesis using an in vitro cachexia model evoked by a co-exposure to TNFα and IFNγ." (PMID 34371902, 2021). "In recent years, research has mainly focused on the role of pro-inflammatory cytokines, such as interleukin-6 (IL-6), interleukin-1 (IL-1), tumor necrosis factor alpha (TNF-α), and interferon gamma (IFN-γ), and confirmed their involvement in the pathogenesis of cachexia." (PMID 34830921, 2021). "The only other potential mediator of the increased ZAG expression in cachexia is interferon-γ (IFNγ), which has been shown to strongly upregulate expression in human epithelial cell lines, and has been suggested to be responsible for the development of cachexia in the Lewis lung tumour model." (PMID 15714206, 2005). "An important phenomenon accompanying cachexia is the inflammatory process, during which the secretion of proinflammatory cytokines is observed, including IL-1β, Il-6, IL8, TNF-α, and interferon-gamma (INF-γ)." (PMID 38610941, 2024).